ANXA3 (annexin A3)
Diseases named in the same sentence as ANXA3 in open-access papers (continued):
Sharing a sentence is not in itself a finding about the gene and the disease.
Sepsis (continued). "Upon reviewing evidence from public transcriptome repositories and the literature, we hypothesize that during sepsis ANXA3 could mediate neutrophils microbicidal activity while also prolonging their survival, and thus also possibly contributing to organ damage." (PMID 32682335, 2020). "Whether ANXA3 upregulation is mediated by IFN in the context of sepsis is unknown." (PMID 32682335, 2020). "An initial literature search returned no known association between ANXA3 and sepsis." (PMID 32682335, 2020). "Thus, we posit that during sepsis ANXA3 might either play a beneficial role, by facilitating microbial clearance and resolution of the infection; or a detrimental role, by prolonging neutrophil survival, which is known to contribute to sepsis‐mediated organ damage." (PMID 32682335, 2020). "Further qRT-PCR validation indicated that four genes are differentially expressed between patients with sepsis and healthy subjects (MMP9, S100A8, S100A9, and ANXA3)." (PMID 32922168, 2020). "The absence of ANXA3 exacerbated sepsis outcomes, including increased mortality, lung injury, leukocyte infiltration, and vascular permeability." (PMID 40151887, 2025). "Previous studies have suggested that lncRNAs may be potential biomarkers for prognosis of sepsis, such as lncRNAs MALAT1, NEAT1, RP11-1220 K2.2.1–7, ANXA3–2, TRAPPC5–1, and ZNF638–1, which have been introduced in introduction." (PMID 34483898, 2021). "According to publicly available transcriptome datasets, the abundance of Annexin A3 (ANXA3) is robustly increased during the course of sepsis; however, no studies have examined the biological significance or clinical relevance of ANXA3 in this pathology." (PMID 32682335, 2020). "Although other annexins such as annexin A3, which has been shown to mediate pathogen clearance and its expression is increased in neutrophils in patients with sepsis, their therapeutic potential in sepsis is currently not clear." (PMID 34566657, 2021). "This function was not investigated in the context of sepsis, but it can be inferred that an increase in ANXA3 abundance in this context may contribute to pathogen clearance and infection resolution." (PMID 32682335, 2020). "Change in ANXA3 abundance as a result of sepsis was thus not mentioned in the title or abstracts of these studies, but those could be identified via a full text search in Google scholar." (PMID 32682335, 2020). "The qPCR results were similar to those acquired from microarray, suggest that the 4 lncRNAs (lncRNA lnc-RP11-1220 K2.2.1–7, lncRNA lnc-ANXA3–2, lncRNA lnc-TRAPPC5–1, lncRNA lnc-ZNF638–1) are significantly highly expressed in septic children and could be novel biomarkers for pediatric sepsis." (PMID 32151258, 2020). "To date, a role for ANXA3 in sepsis has not been reported in the literature." (PMID 32682335, 2020).
pancreatic cancer (10 papers, 2015 to 2024). "Contrariwise, silencing of ANXA3 inhibited the expression of N-cadherin and vimentin in pancreatic cancer, while elevating the expression of E-cadherin." (PMID 34355022, 2021). "Amidst the duct subpopulation markers, Spp1 and Anxa3 caught our eye due to their known roles in pancreatic cancer progression; however, their functions in normal pancreatic duct epithelium have not been fully explored." (PMID 34009124, 2021). "In patients with pancreatic cancer, the expression level of ANXA3 was 1.71 times higher than that in healthy individuals." (PMID 28497041, 2017). "Additionally, ANXA3-knockdown pancreatic cancer cells exhibited decreased expressions of VEGF-C and VEGF-D, both of which are proteins previously shown to be positively associated with the number of lymph node metastases." (PMID 34355022, 2021). "ANXA3 (also known as lipocortin 3) is a calcium-dependent phospholipid-binding protein in the annexin protein family showing over-expression in ovarian, lung, liver, colorectal and pancreatic cancers." (PMID 25978681, 2015). "At molecular level, ANXA3 silencing in pancreatic cancer cells resulted in a decrement of the expression of vascular endothelial growth factor receptor 3 (VEGFR3), which is a protein suggested to play a key role in lymphatic vascularization in pancreatic cancer." (PMID 34355022, 2021). "Additionally, studies encompassing various pancreatic cancer cell lines (CFPAC-1, BxPC-3, PANC-1, SW1990) and 115 patient tissues demonstrated that decreased expression of miRNA-382 correlates with increased levels of ANXA3 (Annexin A3), an activator of the PI3K/AKT pathway." (PMID 39200178, 2024).
gastric cancer (9 papers, 2015 to 2023). A primary or metastatic malignant neoplasm involving the stomach. "Similar upregulation of the expression of ANXA3 is reported in prostate, ovarian, liver, rectal, and gastric cancers." (PMID 28497041, 2017). "Firstly, we determined expression of ANXA3 in 183 gastric cancer tissue samples, and divided these patients into two staining: high ANXA3 staining (n=105) and low ANXA3 staining (n=78)." (PMID 27894078, 2016). "It was reported that the expression of Anxa3 was positively correlated with Ki-67 and Bcl-2 expression in gastric cancer." (PMID 27995049, 2016). "Our research suggests that ANXA3 plays important roles in gastric cancer carcinogenesis and metastasis, and provides a valuable prognostic marker and potential target for treatment of gastric cancer patients." (PMID 27894078, 2016). "In accordance with these previous results, we verified that ANXA3 regulated gastric cancer cell proliferation, migration, and invasion, identifying an attractive strategy to treat in gastric cancer." (PMID 27894078, 2016). "In addition, ANXA3 mRNAs and proteins were overexpressed in gastric cancer tissues and various gastric cancer cell lines, as detected by RT-PCR and Western blot analyses." (PMID 34355022, 2021). "Moreover, the expression of Anxa3 was reported to be positively correlated with Ki-67 expression in gastric cancer." (PMID 27995049, 2016). "As found, the upregulation of Anxa3 expression could promote the development of colorectal cancer and gastric cancer and enhance the metastatic activity of LADC." (PMID 27995049, 2016). "Similarly, the identification of SNPs in the Anxa3 gene locus may imply roles in gastric cancer." (PMID 33810523, 2021). "This study aims to investigate the significance of ANXA3 expression and the mechanism by which ANXA3 is involved in the epithelial–mensenchymal transition (EMT) of gastric cancer cells." (PMID 27894078, 2016). "However, the specific mechanism involved in ANXA3 promoting gastric cancer cell metastasis has not been clarified." (PMID 27894078, 2016).
lung adenocarcinoma (8 papers, 2011 to 2022). A carcinoma that arises from the lung and is characterized by the presence of malignant glandular epithelial cells. "Biomarkers for PCa also include PSA (Prostate Specific Antigen) and ANXA3 (Annexin A3), the latter also being expressed in lung adenocarcinoma." (PMID 35494646, 2022). "Our previous study identified an elevated abundance of annexin A3 (Anxa3) as a novel prognostic biomarker of lung adenocarcinoma (LADC) through quantitative proteomics analysis." (PMID 27995049, 2016). "Annexin A3 has been previously identified as an oncoprotein, based on its overexpression in lung adenocarcinoma and its ability to promote lymph node metastasis." (PMID 24260057, 2013). "Thus, given its important role in lung adenocarcinoma progression, ANXA3 might serve as a novel prognostic biomarker for this cancer." (PMID 22229091, 2011).
liver cancer (7 papers, 2016 to 2023). An epithelial or non-epithelial malignant neoplasm that arises from the liver. "In liver cancer PROM1 was more strongly co-expressed with a larger number of genes, including CFTR, KRT7, ANXA3, TACSTD2, and FZD1." (PMID 31164716, 2020). "ANXA3 has been reported that increased in HCC and as a potential target for immunotherapy of liver cancer stem-like cells." (PMID 27894078, 2016). "Also, the expression of ANXA3 which promotes angiogenesis, drug resistance, and stemness in HCC, and the expression of KLF4 which is one of the Yamanaka factors that also regulates liver cancer stem cell plasticity, increased upon regorafenib treatment." (PMID 34458250, 2021).
acute myocardial infarction (5 papers, 2019 to 2025). Necrosis of the myocardium, as a result of interruption of the blood supply to the area. "Annexin A3 is also highly expressed in myocardial infarction, and silencing Annexin A3 promotes myocardial repair after acute ischemic injury through activation of the PI3K/AKT pathway." (PMID 39765837, 2024). "ANXA3 and SOCS3, as novel biomarkers for acute myocardial infarction (AMI), demonstrates significantly superior diagnostic performance compared to traditional markers CD34 and FLT3, with area under the ROC curve (AUC) exceeding 0.7, highlighting their stronger clinical relevance." (PMID 40760666, 2025). "AnxA3 is also highly expressed in myocardial cells during acute myocardial infarction and in vivo AnxA3 inhibition using a short hairpain RNA in rats reduced infarct size, inflammatory response, α-actin, collagen type I and III by activation of the PI3K/Akt signaling pathway." (PMID 36313572, 2022).
colon cancer (5 papers, 2017 to 2025). "A few examples of TAAs identified using proteomics include the markers PSMA1, LAP3, ANXA3, and maspin, which were identified by one group as biomarkers for colon cancer." (PMID 30804938, 2019). "ANXA3 was detected in the colon cancer tissues of all 8 patients, although the overall expression levels were of weak to medium intensities and predominantly cytoplasmic." (PMID 29423100, 2018). "We then used this approach to discover a set of cancer-immunogenic proteins in colon cancer (maspin, ANXA3, LAP3, and PSMA1) and showed that these proteins are overexpressed in the tumor, pointing to a possible abundance mechanism by which these proteins become immunogenic." (PMID 29423100, 2018). "Overall, expression of maspin, ANXA3, LAP3, and PSMA1 was increased in colon cancer tissue extracts." (PMID 29423100, 2018). "Of these, maspin, ANXA3, LAP3, and PSMA1 were reproducibly discovered as serum-reactive in all 3 initially tested cancer samples, including colon tumor tissue from the 2 patients and the liver metastatic tissue from the patient with primary colon cancer and secondary liver metastasis." (PMID 29423100, 2018).
bladder cancer (4 papers, 2018 to 2023). "Investigators from this study further suggested that ANXA3 might serve as a reliable non-invasive diagnostic biomarker for bladder cancer." (PMID 34355022, 2021). "Likewise, markedly elevated ANXA3 expression was detected in bladder cancer by multiplexed liquid chromatography multiple-reaction-monitoring mass spectrometry assay (LC-MRM-MS)." (PMID 34355022, 2021). "Western blotting showed that urinary ANXA3 and HSPE1 protein levels were higher in bladder cancer samples than in hernia samples, and enzyme-linked immunosorbent assays confirmed a higher urinary concentration of HSPE1 in bladder cancer than in hernia, hematuria and urinary tract infection." (PMID 30112103, 2018). "The expression of ANXA1, ANXA2, ANXA3, ANXA5, ANXA6, ANXA8, and ANXA13 was closely related to basal-subtype bladder cancer, while the expression of ANXA4, ANXA9, ANXA10, and ANXA11 was closely related to luminal-subtype BC." (PMID 34484309, 2021). "ANXA3 (annexin A3) and HSPE1 (heat shock protein family E member 1), which showed the highest detection frequency in bladder cancer samples, were selected for further validation." (PMID 30112103, 2018). "ANXA1, ANXA2, ANXA3, ANXA5, ANXA6, ANXA7, and ANXA9 had prognostic value in bladder cancer." (PMID 34484309, 2021). "We used TCGA data to find that in addition to ANXA1 and ANXA2, other ANXA family proteins (ANXA3, ANXA5, ANXA6, and ANXA9, which have not been studied) are also closely related to the prognosis of bladder cancer." (PMID 34484309, 2021).
lymph node metastases (4 papers, 2011 to 2023). "In our previous study, annexin A3 (Anxa3) was identified as a novel metastasis-related protein in LADC using quantitative proteomics, and its high expression was found to be correlated with lymph node metastasis, advanced tumor stage, recurrence, and poor prognosis." (PMID 27995049, 2016).
renal carcinoma (4 papers, 2015 to 2023). A carcinoma arising from the epithelium of the renal parenchyma or the renal pelvis. "As well, ANXA3, whose decrease was associated with renal cancer development, was also augmented." (PMID 26551931, 2016). "While on the other hand, decreased ANXA3 expression was negatively correlated with the progression of prostate and renal carcinoma." (PMID 29443940, 2018). "In contrast, decreased ANXA3 expression negatively correlates with the development of prostate and renal carcinoma." (PMID 26475168, 2015). "Immunohistochemistry and immunofluorescence analyses for ClC-5, megalin, cubilin, ANXA3, podocalyxin, CD24, CD44, HSA, and LTA marker were performed on 23 kidney biopsies from patients with Lupus Nephritis and 9 control biopsies (obtained from nephrectomies for renal cancer)." (PMID 37594671, 2023).
renal cell carcinoma (4 papers, 2016 to 2024). "The expression of 36 kDa AnxA3 is significantly decreased in renal cell carcinoma (ccRCC), while the expression of 33 kDa AnxA3 is increased, resulting overall decrease in AnxA3 expression." (PMID 38544804, 2024). "A study by Bianchi C indicated that ANXA3 is participated in Renal cell carcinoma metastasis through stimulating angiogenesis by increased VEGF level promoted by HIF-1a." (PMID 27894078, 2016). "Paradoxically, a negative relationship between the expressions of ANXA3 and HIF1α has been reported in renal cell carcinoma (RCC)." (PMID 34355022, 2021).
rheumatoid arthritis (4 papers, 2015 to 2022). A chronic, systemic autoimmune disorder characterized by inflammation in the synovial membranes and articular surfaces. "An SNP extracted using the combined method, rs2867461 in ANXA3, was previously reported as a genetic factor associated with rheumatoid arthritis, systemic lupus erythematosus, and Graves’ disease in a Japanese population." (PMID 26475168, 2015). "Among the BRGs, ANXA3 is associated with rheumatoid arthritis in Japanese." (PMID 28771541, 2017). "The gene expression was exclusively restricted to neutrophils, it’s reported that the ANXA3 participate in the formation of NETs in several diseases such as rheumatoid arthritis and systemic lupus erythematosus." (PMID 35252353, 2022).
schizophrenia (4 papers, 2022 to 2025). A major psychotic disorder characterized by abnormalities in the perception or expression of reality. "A key challenge of this study is that the decreased ANXA3 levels in MDD parallel the findings in schizophrenia and bipolar disorder, suggesting its potential as a cross-diagnostic biomarker for these disorders." (PMID 41010398, 2025). "ANXA3 has been studied in various neuroinflammatory diseases, such as schizophrenia, traumatic brain injury, and cerebral small vessel disease." (PMID 38102696, 2023). "We then observed significant overlap (three overlapping genes (IFIT2, IFIT3, and ANXA3; OR = 77.4, P = 7.4e−5) between RP5-998N21.4OE-induced DEGs in SK-N-SH cells and RP5-998N21.4-coexpressed schizophrenia-associated DEGs in twin subjects." (PMID 35232977, 2022). "Collectively, these results indicate that RP5-998N21.4 might regulate immune defense-related pathways by promoting the transcription of IFIT2, IFIT3, or ANXA3, which are involved in the pathophysiology of schizophrenia." (PMID 35232977, 2022).
Cerebral ischemia (3 papers, 2021 to 2023). Restriction of arterial blood supply to the brain associated with insufficient oxygenation to support the metabolic requirements of the tissue. "ANXA3 is recognized as a regulator of cerebral ischemia/reperfusion injury." (PMID 36952494, 2023). "Indeed, in previous work on experimental stroke, we identified ANXA3 as a novel marker of phagocytic microglia after cerebral ischemia." (PMID 32378028, 2021).
diabetes (3 papers, 2020 to 2023). "Although dysregulation of ANXA1 and ANXA2 has been documented in diabetes, changes in ANXA3 have not been reported." (PMID 37895816, 2023). "In a small study (six unions and six non-unions, with half of the patients in each group having type 2 diabetes mellitus), Annexin A3 (ANXA3) was found to be significantly upregulated in blood samples of patients with non-unions compared with fracture unions." (PMID 36671657, 2023).
ischemic stroke (3 papers, 2020 to 2023). A stroke disorder caused by obstruction of blood flow to the brain, due to thrombotic (local blood clot formation) or embolic (due to a blood clot or other material traveling from another site) event. "Third, more in vivo and in vitro studies are needed to clarify the underlying mechanism of these correlations among ADM, ANXA3, SLC22A4 and VIM and infiltrated immune cells in ischaemic stroke." (PMID 35962388, 2022). "In summary, we determined that ADM, ANXA3, SLC22A4 and VIM are diagnostic markers of ischaemic stroke." (PMID 35962388, 2022). "These included genes that have been previously associated with CVD in human studies such as PTX3 (pentraxin 3) and S100A12 (EN-RAGE), as well as genes that have been associated with CVD only in animal studies such as ANXA3 and SLPI, both shown to be up-regulated in rodent models of ischemic stroke." (PMID 32780732, 2020). "The mechanism underlying the relationship between ADM, ANXA3, SLC22A4 and VIM and immune cells may be of great significance for the pathogenesis and progression of ischaemic stroke, and related research of these genes could provide new therapeutic insight for ischaemic stroke." (PMID 35962388, 2022). "Eight hub genes (ADM, ANXA3, CARD6, CPQ, SLC22A4, UBE2S, VIM and ZFP36) were revealed to be significantly correlated with ischaemic stroke by the LASSO logistic regression and SVM-RFE algorithm." (PMID 35962388, 2022). "The expression levels of the ADM, ANXA3, CARD6, CPQ, SLC22A4 and VIM genes were significantly increased in the ischaemic stroke patients compared with those in the healthy subjects (p < 0.05–0.01)." (PMID 35962388, 2022). "The ROC analyses based on the training set, validation set, and our clinical samples showed that the ADM, ANXA3, SLC22A4 and VIM genes remained highly effective in distinguishing the ischaemic stroke patients from the normal subjects." (PMID 35962388, 2022). "Eight hub genes (ADM, ANXA3, CARD6, CPQ, SLC22A4, UBE2S, VIM and ZFP36) were revealed to be significantly correlated with ischaemic stroke by a LASSO logistic regression and SVM-RFE machine learning methods." (PMID 35962388, 2022). "Further verifying the expression levels of these key genes in ischaemic stroke patients, we noticed that the expression levels of ADM, ANXA3, SLC22A4 and VIM were significantly increased in the ischaemic stroke patients compared with those in the normal subjects (p < 0.01)." (PMID 35962388, 2022). "Therefore, further studies are needed to explore whether therapies targeting these genes such as ADM, ANXA3, SLC22A4 and VIM will bring some similar risks to patients with ischaemic stroke." (PMID 35962388, 2022).
laryngeal squamous cell carcinoma (3 papers, 2024). A squamous cell carcinoma that arises from the larynx. "Proteomic analysis of TAMs isolated from laryngeal squamous cell carcinoma (LSCC) tissue from patients with lymphatic metastasis demonstrated that annexin A3 (ANXA3) was upregulated." (PMID 39726782, 2024). "Tumor-associated macrophages (TAM) produce exosomes rich in annexin A3 (ANXA3), acting on laryngeal squamous cell carcinoma (LSCC) cells and inhibiting their ferroptosis." (PMID 39223632, 2024). "Recent studies in mouse models of laryngeal squamous cell carcinoma have shown that exosomes secreted by M2 macrophages, rich in annexin A3 (ANXA3), enhance the synthesis of GSH and promote intracellular iron accumulation, thereby increasing tumor cell resistance to ferroptosis." (PMID 39575419, 2024).